MIR9-1 (microRNA 9-1)
Synonyms: hsa-mir-9-1; MIRN9-1; miRNA9-1; mir-9-1
Gene: MicroRNA gene on chromosome 1 (156,420,341 to 156,420,429, reverse strand). Ensembl gene ENSG00000207933.
Pathways (Reactome):
Cell-Cell communication: Regulation of CDH1 mRNA translation by microRNAs
Gene Ontology:
Biological process: miRNA-mediated post-transcriptional gene silencing
Cellular component: RISC complex
Homologues: Orthologues: chimpanzee ptr-mir-9-1 (100% identical), mouse Mir9-1 (100% identical), guinea pig MIR9-1 (99% identical), tropical clawed frog xtr-mir-9a-1 (92% identical), zebrafish dre-mir-9-1 (87% identical). Paralogues in human: MIR9-2 (82% identical), MIR9-3 (78% identical).
Diseases named in the same sentence as MIR9-1 in open-access papers:
MIR9-1 is named in the same sentence as 8 diseases in open-access papers, as found by Europe PMC text mining. Sharing a sentence is not in itself a finding about the gene and the disease. The quoted sentences say what the papers report.
Huntington disease (1 paper, 2023). Huntington disease (HD) is a rare neurodegenerative disorder of the central nervous system characterized by unwanted choreatic movements, behavioral and psychiatric disturbances and dementia. "Community-three-associated ncRNAs included Huntington’s disease-related MIR9-1, which was negatively associated with mtOCR, and anti-inflammatory-associated MIRLET7A1 and cell migration lncRNA DEPDC1-AS1, which were positively associated with mtOCR." (PMID 37107179, 2023).
ovarian tumors (1 paper, 2022). "In addition, in peritoneal metastases, we observed a significant decrease in methylation levels of MIR193A (p = 0.04) and MIR9-1 (p = 0.007, FDR = 0.05), which were significantly hypermethylated both at the stage of the onset of primary ovarian tumors and at the stage of their metastasis." (PMID 35163224, 2022).
tumour (1 paper, 2017). "A statistically significant difference in methylation frequency between normal and tumour samples was detected only for the MIR9-1 promoter (NBTs 0/10, Tumour 43/101, p = 0.006)." (PMID 28345661, 2017).
MIR9-1 also shares sentences with these, for which no sentence is quoted: cancer (2 papers); leukoplakia (1); metastatic tumors (1); periodontitis (1); secondary tumors (1).